STIM1 (stromal interaction molecule 1)
Diseases named in the same sentence as STIM1 in open-access papers (continued):
Sharing a sentence is not in itself a finding about the gene and the disease.
hepatocellular carcinoma (26 papers, 2013 to 2025). A malignant tumor that arises from hepatocytes. "This classical model of STIM1 and Orai1 has been extensively implicated in tumorigenesis of many cancers, including hepatoma, breast, colorectal, prostate, etc., Orai proteins and STIM proteins represent attractive therapeutic targets." (PMID 35269437, 2022). "In hepatoma cell lines (Huh-7 and HepG2), simultaneous knockdown of STIM1 and ORAI1 dropped protein levels of cyclin D1, thus causing G0/G1 cell cycle arrest." (PMID 34572262, 2021). "The similar roles of STIM1 in focal adhesion turnover and cell migration were also found in hepatocellular carcinoma cells." (PMID 31252656, 2019). "In hepatocellular cancer cells, hypoxia also activates an ER Ca2+ sensor, stromal interaction molecule 1 (STIM1), which mediates activation of store-operated Ca2+ entry (SOCE) and leads to upregulation of hypoxia-inducible factor 1 (HIF-1) expression." (PMID 29636894, 2018). "Silencing of STIM1 has also been shown to inhibit hepatocellular carcinoma cell proliferation by cell cycle arrest." (PMID 27443843, 2016). "Additional studies showed that knocking down STIM1 resulted in reduced cancer metastasis in colorectal cancer, melanoma and hepatocellular carcinoma." (PMID 27863410, 2016). "Previous experimental studies showed that suppression of STIM1 inhibited cell proliferation of glioblastoma, melanoma, hepatocellular carcinoma, human epidermoid carcinoma and hypopharyngeal carcinoma." (PMID 27863410, 2016). "The purpose of this study is to investigate possible HBV origins of specific microRNAs we identified in a stem cell-like subpopulation of Huh-7 hepatocellular carcinoma (HCC) cell lines with enhanced STIM1 and/or Orai1 expression that mimicked poor cancer prognosis." (PMID 36556285, 2022). "Moreover, Stim1 expression is found to increase in hepatoma tissues than in precancerous tissues, and blockade of Stim1‐mediated SOCs inhibits migration and invasion of hepatocarcinoma cells." (PMID 27878958, 2017). "Decreased TRPC1 may be compensated by increased expression of STIM1 that possibly takes part in the up-regulation of SOC entry in TRPC1-silenced hepatocellular carcinoma cells." (PMID 27443843, 2016). "In hepatoma cells, ORAI1 and STIM2 adapter protein were the predominant forms, while in HepaRG cells, transcription of ORAI3 and STIM1 was much higher, as revealed in RNAseq dataset and by real-time PCR." (PMID 37189460, 2023). "Our earlier study reported that hypoxia-inducible factor-1 (HIF-1) could transcript STIM1 to enhance the SOCE in hepatocellular carcinoma (HCC) cells." (PMID 37932320, 2023). "STIM1 and Orai1-mediated SOC entry is apparent in vascular smooth muscle proliferation, but also plays a role in hepatocellular carcinoma cell migration and invasion." (PMID 27443843, 2016). "Reciprocal alterations in the levels of TRPC1 and STIM1 have been observed, suggesting their interaction in regulating SOC entry in Huh7 hepatocellular carcinoma cells." (PMID 27443843, 2016). "Indeed, the STIM1-mediated SOCE activation promotes migration and invasion in hepatocellular carcinoma cells by modulating the focal adhesion turnover." (PMID 36677874, 2023). "Therefore, this study investigated the functional consequences of enhanced expression of STIM1 and Orai1 in a tumor-initiating subpopulation of Huh-7 hepatocellular carcinoma (HCC) cells that express epithelial cell adhesion molecule (EpCAM) and Prominin 1 (CD133)." (PMID 31366337, 2019). "Moreover, in human hepatoma cell line Huh-7, it has been also shown that Ca2+ entry involving TRPC6, together with STIM1 and Orai1, increases cyclin D1 expression." (PMID 24058448, 2013). "STIM1 promotes autophagy and epithelial-mesenchymal transition in hepatocellular carcinoma by interacting with LC3B through its SAM domain, offering a potential target to inhibit HCC metastasis." (PMID 39315094, 2024).
hepatocellular carcinoma (continued). "In non-excitable cells, such as hepatocellular carcinoma (HCC) cells, the primary pathway for Ca2+ influx is through stromal interaction molecule 1 (STIM1)-mediated store-operated calcium entry (SOCE)." (PMID 39281833, 2024). "STIM1 was downregulated in metastatic hepatocellular carcinoma (HCC) rather than in primary HCC cells." (PMID 38532463, 2024). "In this study, we systematically evaluated the genetic susceptibility between the store-operated calcium (SOC) influx pathway (stromal interaction molecule 1 (STIM1) and ORAI1) and human hepatocellular carcinoma (HCC) in patients with chronic hepatitis B (CHB) infection." (PMID 33182378, 2020). "Stromal-interaction molecule 1 (STIM1) triggered store-operated Ca2+ entry (SOCE) is the major route of Ca2+ influx for non-excitable cells including hepatocellular carcinoma (HCC) cells." (PMID 32483465, 2020). "First, they are differentially expressed in malignant cells and STIM1 and ORAI1 were found to be more strongly expressed in hepatoma tissues than in pre-cancerous tissues or non-tumoral tissues from the same patients." (PMID 30338034, 2018).
melanoma (24 papers, 2013 to 2026). A malignant, usually aggressive tumor composed of atypical, neoplastic melanocytes. "Accordingly, we investigated potential STIM1-mediated cell-cell interactions by associating malignant-derived STIM1 scores with metagenes from 277 bulk TCGA melanoma transcriptomes with tumor purity (IHC) > 80%." (PMID 33859736, 2021). "Herein, we developed a computational pipeline to determine cell-specific transcriptional profiles that associated with STIM1 expression in human melanoma." (PMID 33859736, 2021). "In light of the fact that STIM1 plays a critical role in immunity and has been linked with many cancers, our findings depicted its potential mechanisms in human melanomas." (PMID 33859736, 2021). "Thus, how to systematically characterize the cellular functions associated with STIM1 expression in malignant melanoma cells remains challenging." (PMID 33859736, 2021). "We tested whether STIM1-mediated cellular programs are associated with overall survival (OS) of melanoma patients." (PMID 33859736, 2021). "Utilizing a bottom-up approach starting with STIM1 expression status, we identified genes that are co-expressed (positively and significantly associated) with STIM1 in diverse cell types in melanoma and constructed STIM1 scores to explore the biological relevance." (PMID 33859736, 2021). "Here, since the major aim of this study is to characterize the STIM1-associated cellular programs in TME of melanoma, we selected to deliberate on SCGs (and STIM1 score), which may capture both Ca2+-dependent and Ca2+-independent pathways across diverse cell types." (PMID 33859736, 2021). "Therefore, whether more gain-of-function mutations of STIM1 in melanoma tumors is worth for investigation in the future." (PMID 33859736, 2021). "Plateau phases in melanoma cells are produced by STIM1/ORAI1 store-operated Ca2+ entry and mechanosensitive TRPM7/TRPV4 channels, which transform perivascular forces and osmotic conditions into electrical signals." (PMID 41463339, 2025). "Orai- and STIM1-mediated Ca2+ oscillation signals were reported to facilitate invadopodium assembly and thus promote melanoma invasion by regulating the recycling of membrane-bound MT1-MMP and extracellular matrix (ECM) remodeling." (PMID 35162934, 2022). "In most cancer types, including breast, gastric, glioblastoma, melanoma, and renal cancer, migration and metastasis have been identified to be controlled by both STIM1 and Orai1." (PMID 36612099, 2022). "Inhibition of SOCE by knockdown of STIM1 or Orai or by SOCE inhibitors suppresses melanoma cell proliferation and migration, while induction of SOCE activates ERK, which is inhibited by calmodulin kinase II or Raf-1 inhibitors." (PMID 35162934, 2022). "In melanoma cells, STIM1- and Orai1-dependent regulation of proliferation occurs through the CaMKII/Raf-1/ERK signaling pathway." (PMID 36612099, 2022). "The results from current study imply that STIM1 expression in melanoma affects cellular physiology in a cell-specific manner." (PMID 33859736, 2021). "Our analysis further links STIM1 score to the abundance of immune cells in melanoma tissues, providing another mechanistic link between STIM1 and immune-related pathways." (PMID 33859736, 2021). "A curated list of ligand-receptor interactions 41 was adopted to pinpoint receptor gene(s) that correspond to STIM1-coexpressed cytokines/chemokines (i.e., ligands secreted from malignant melanoma cells)." (PMID 33859736, 2021). "Further integration of SCGs from diverse cell types to the expression of bulky tumors links the functions of STIM1 to patient prognosis and illustrates the cellular ecosystem in melanoma." (PMID 33859736, 2021). "In summary, this study advances the understanding of cell-specific STIM1-dependent biological alterations in human melanoma." (PMID 33859736, 2021). "In bulky malignant melanoma tissues, the expression of STIM1 in malignant cells is likely to be masked by other cell types (e.g., immune cells)." (PMID 33859736, 2021).
melanoma (continued). "In this study, we make the first connection between malignant STIM1 expression and immune regulation in melanoma tissues." (PMID 33859736, 2021). "To answer these questions, we dissected cell-specific STIM1-associated cellular programs in diverse cell types within the melanoma tumor microenvironment by measuring cell-type specificity of STIM1 expression and SCGs." (PMID 33859736, 2021). "By leveraging single-cell melanoma expression data, we firstly identified gene profiles that are significantly co-expressed with STIM1 in different cell types, defining module genes as those ranked as most significant for each cell type." (PMID 33859736, 2021). "To do so, we constructed a malignant-cell-derived STIM1 score from 277 melanoma specimens with tumor purity (IHC) > 80% (44 primary and 233 metastatic) by averaging the top 100 malignant-cell-derived STIM1-coexpressed profiles." (PMID 33859736, 2021). "Correlation of clinical outcomes from the TCGA melanoma dataset with malignant-cell-derived STIM1 scores were conducted." (PMID 33859736, 2021). "We found that expressions of STIM1 both at the mRNA and protein levels were dramatically increased in vemurafenib-resistant melanoma cells." (PMID 34570440, 2021). "In particular, in the example of the unbiased ribozyme screen using a weak melanoma cell line that identified STIM1 as a tumor suppressor." (PMID 34069353, 2021). "To directly compare the malignant-cell-derived STIM1 scores from malignant tissue and normal counterparts, we next interrogated an expression dataset that comprised 45 bulky primary melanoma tumors and 7 normal skin lesions (GSE3189)." (PMID 33859736, 2021). "We imply that immune crosstalk in melanoma tissues is presented when immune cells in TME possess receptors complemented with ligands secreted from STIM1-mediated cytokine genes." (PMID 33859736, 2021). "In melanoma, STIM1 blockade the recycling of MT1-MMP to the plasma membrane, thus inhibiting the breakdown of the extracellular matrix." (PMID 34155535, 2021). "Collectively these studies show that the expression of STIM1 has differential effects in different cancers and sometimes as is the case for melanomas in the same cancer type." (PMID 34069353, 2021). "For example, STIM1 knockdown accelerated the motility of melanoma cells, while STIM1 overexpression induced growth arrest of G401 rhabdoid tumor, rhabdomyosarcoma and rodent myoblast cell lines." (PMID 31564210, 2019). "Mechanistically, STIM1/Orai1-mediated Ca2+ oscillations promoted the assembly of invadopodia precursors in melanoma cells by activating Src kinase." (PMID 31252656, 2019). "The importance of Ca2+ flux in regulating melanoma proliferation and cell migration was previously suggested by experiments including a knockdown of STIM1 or Orai1 in human melanoma cell lines as well as a pharmacological inhibitor of SOCE." (PMID 29568366, 2018). "We found that STIM1 and Orai1 isoforms were abundantly expressed in human melanoma tissues and multiple melanoma/melanocyte cell lines." (PMID 24586666, 2014). "Ca2+ peak amplitude in the SOCE phase was lower in both STIM1- and Orai1- knockdown cells than in control metastatic melanoma cell lines." (PMID 24586666, 2014). "SOCE activity in melanoma cells was dependent on STIM1 and Orai1, and was reduced by SOCE inhibitor YM58483." (PMID 24586666, 2014). "STIM1 and Orai1 were expressed not only in cultured melanoma cells, but also in human melanoma tissues." (PMID 24586666, 2014). "Western blot analyses showed that STIM1 and Orai1 are expressed in metastatic human melanoma cell lines, while the melanocyte cell line, HEMA-LP, displayed only a low level of Orai1 expression." (PMID 24586666, 2014). "Our data demonstrate that STIM1 and Orai1 have roles in proliferation and migration of various melanoma cell lines, indicating that SOCE contributes to melanoma progression." (PMID 24586666, 2014).
melanoma (continued). "Orai1- and STIM1-mediated Ca2+ oscillations regulate melanoma ECM degradation by MT1-MMP." (PMID 35162934, 2022). "Notably, among pyrazoles, BTP2/Pyr2 and Pyr3 can block Orai1, TRPC3, and STIM1 and inhibit melanoma." (PMID 36612099, 2022). "Accordingly, STIM1 knockdown significantly reduces the metastatic ability of melanoma cells." (PMID 36158191, 2022). "Integration of malignant-cell-derived SCGs with data from bulk melanoma specimens and Reactome pathways further connects STIM1 to alterations in calcium signaling, cell cycle regulation, and unexpectedly, immune-related cellular pathways in malignant melanoma cells." (PMID 33859736, 2021). "In addition, malignant-cell-derived STIM1 score level was significantly different across melanomas and benign nevi tissue (Mann-Whitney test p-values < 0.05; from GSE4587 and GSE3189)." (PMID 33859736, 2021). "However, we didn't observe significant difference in malignant-cell-derived STIM1 score level between melanomas and normal melanocytes (Mann-Whitney test p-values > 0.05; from GSE4587 and GSE4570)." (PMID 33859736, 2021). "Therefore, levels of malignant-derived STIM1 score in melanoma, nevi (benign) and melanocytes (normal) were compared by using several melanoma expression datasets (including GSE4587, GSE4570 and GSE3189)." (PMID 33859736, 2021). "In melanoma cells, STIM1 and Orai1 have been reported to play a role in migration." (PMID 33333945, 2020). "While changes in the expression and function of STIM1 and Orai1 have been found in a range of cancer types and thus implicated in disease progression, levels of STIM1 and Orai1 were not different between malignant and non-malignant melanoma cells." (PMID 29568366, 2018). "We also examined expression of STIM1 and Orai1 in human melanoma tissues, using a microarray." (PMID 24586666, 2014). "Finally, we investigated whether STIM1-coexpressed genes (SCGs) in each cell type could serve as prognostic indicators for melanoma patients." (PMID 33859736, 2021). "Therefore, malignant cell types may be a good starting point to investigate the functional versatility of STIM1 expression in melanoma." (PMID 33859736, 2021). "Indeed, knockdown of STIM1 and Orai1 reduced the migration of melanoma cells." (PMID 33333945, 2020). "Furthermore, knockdown of STIM1 expression accelerated motility of melanoma cells, indicating that STIM1 may be an anti-metastasis gene." (PMID 31564210, 2019). "Indeed, knockdown of STIM1 inhibited melanoma lung metastasis in a mouse xenograft model." (PMID 27417567, 2016). "We examined whether SOCE in melanoma cell lines is regulated by STIM1 and Orai1." (PMID 24586666, 2014). "High levels of STIM1, STIM2 and SOCE were also documented in metastatic melanoma as compared to primary melanoma and knockdown of Orai1 and/or STIM2 reduced melanoma cell migration and invasiveness." (PMID 34069353, 2021). "By using single-cell transcriptomic profiles to define the role of STIM1 expression in specific cells, we provide a systems-level view of STIM1-mediated cellular programs in TME of melanoma." (PMID 33859736, 2021). "A recent study demonstrated that STIM1- and Orai1-mediated SOCE promotes melanoma invasion and ECM degradation by increasing invadopodia formation and activity." (PMID 28912430, 2017). "They found that STIM1 and ORAI1 were expressed at high levels in human melanomas and melanoma cell lines." (PMID 25710007, 2015). "We found that STIM1 and STIM2 in T cells are required to curtail tumour growth in animal models of melanoma and adenocarcinoma." (PMID 23922331, 2013). "We thus provide a method to dissect malignant-cell-specific STIM1-dependent cellular programs in bulky melanoma tissues, which is difficult to accomplish without single-cell level data." (PMID 33859736, 2021).
melanoma (continued). "Construction of a STIM1 score (derived from non-malignant cells) in bulky melanoma tissues with available clinical data allowed us to examine the correlation between patient survival and STIM1-mediated cellular programs from non-malignant cell types." (PMID 33859736, 2021). "A role for STIM1 and Orai1-mediated Ca2+ oscillations was further demonstrated in the context of cell invadopodium assembly and extracellular matrix (ECM) degradation in models of melanoma metastasis." (PMID 27417567, 2016). "Since STIM1 and Orai1 were detected in human melanoma tissues, we examined whether SOCE occurs in melanoma cell lines." (PMID 24586666, 2014). "In contrast, Orai1-knockdown inhibited proliferation in C8161 cells but not in SK-Mel-2 or SK-Mel-24 cells, suggesting that STIM1, rather than Orai1, is the key determinant of melanoma proliferation." (PMID 24586666, 2014). "Notably, unlike the melanoma lines characterized in, STIM1 and Orai1 were found to be highly expressed in melanoma, but no expression of their homologs was observed." (PMID 27417567, 2016). "Interestingly, STIM1, but not Orai1, showed higher expression in metastatic melanoma than in primary melanoma." (PMID 24586666, 2014). "Importantly, when we compared the growth of B16-Ova melanomas in mice that had received either no CTLs, wildtype CTLs or DKO CTLs, we observed a complete failure of STIM1/2-deficient CTLs to prevent tumour progression." (PMID 23922331, 2013). "Using conditional knock out mice lacking STIM1 and its homologue STIM2, we find that SOCE in CD8+ T cells is required to prevent the engraftment of melanoma and colon carcinoma cells and to control tumour growth." (PMID 23922331, 2013). "As a consequence, CTL lacking both Stim1 and Stim2 genes and therefore CRAC channel function failed to control the growth of melanoma and colon carcinoma cells and to prevent tumour engraftment." (PMID 23922331, 2013). "Finally, overexpression of STIM1 and Orai1 failed to restore SOCE in any of the Wnt5a-expressing invasive melanoma cell lines examined." (PMID 27417567, 2016).